KLF9 (KLF transcription factor 9)
Diseases named in the same sentence as KLF9 in open-access papers (continued):
Sharing a sentence is not in itself a finding about the gene and the disease.
renal cell carcinoma (5 papers, 2016 to 2025). "It was reported that the development and metastasis of renal cell carcinoma were promoted by the miR-140-5p/KLF9/KCNQ1 axis, revealing a novel pathogenic mechanism underlying renal cell carcinoma." (PMID 38807370, 2024). "We noticed that several stress response genes such as Drr1 (down-regulated in renal cell carcinoma 1, also called family with sequence similarity 107 (Fam107A)), Edn1, Klf9, and Nfkbia39, 40, 41, 42 were significantly increased in Cpeb4GT/GT spinal cord, which was independently validated by RT-qPCR." (PMID 27381259, 2016). "In renal cell carcinoma (RCC), KLF9 serves as a critical regulator of cell proliferation, migration, and invasion." (PMID 40860800, 2025).
diabetic cardiomyopathy (4 papers, 2022 to 2024). Diabetic cardiomyopathy is a disorder of the heart muscle in people with diabetes. "In mice injected with a PPARγ inhibitor, the protective effects of KLF9 knockdown on diabetic cardiomyopathy were counteracted by GW9662 injection." (PMID 36359788, 2022). "In this study, we first identified the role of KLF9 in a cardiovascular disease: diabetic cardiomyopathy." (PMID 36359788, 2022). "Therefore, reduced KLF9 expression regulates autophagy in cardiomyocytes and exacerbates diabetic cardiomyopathy." (PMID 38516000, 2024). "Furthermore, the SGLT-2 inhibitor promoted cardiomyocyte autophagy by blocking miRNA-30d expression, and miRNA-30d negatively regulated KLF9, thereby improving cardiac function in diabetic cardiomyopathy mice." (PMID 38516000, 2024). "KLF9 was upregulated in the hearts of mice with diabetic cardiomyopathy and in cardiomyocytes." (PMID 36359788, 2022). "In this study, we aimed to explore the effect of KLF9 on diabetic cardiomyopathy." (PMID 36359788, 2022). "In addition, KLF9 overexpression in the heart deteriorated cardiac function and aggravated hypertrophic fibrosis, the inflammatory response and oxidative stress in mice with diabetic cardiomyopathy." (PMID 36359788, 2022). "KLF9 may become a therapeutic target for diabetic cardiomyopathy." (PMID 36359788, 2022). "Further, inflammation and oxidative stress are the main features of diabetic cardiomyopathy (DCM), and Klf9 expression was found to be upregulated in DCM." (PMID 38003466, 2023).
Endometrial tumors (4 papers, 2008 to 2023). "Endometrial tumors had markedly reduced levels of KLF9 mRNA and protein when compared to paired normal endometrial tissue." (PMID 38067370, 2023). "Consistent with this, endometrial tumors of higher grades (and with greater invasion and metastasis) had decreased KLF9 gene expression compared to normal endometrium and stage I tumors." (PMID 18783612, 2008). "The first hints of any kind of tumor-suppressive function for KLF9 were reported in 2008 and 2011; in these reports, KLF9 mRNA and protein levels were shown to be significantly reduced in human endometrial tumors when compared to adjacent uninvolved endometrium." (PMID 38067370, 2023). "Human endometrial tumors of high tumor grade had decreased KLF9 mRNA abundance." (PMID 18783612, 2008). "Given that KLF9 over-expression increased proliferation, and induced the expression of transcripts encoding multiple ECM and basement membrane components for increased adhesion to substratum in HEC-1-A cells, it was of interest to examine human endometrial tumors for expression of KLF9 mRNA." (PMID 18783612, 2008). "Endometrial tumors obtained at surgery (MET, n = 4; CON, n = 4) were analyzed for proliferation (Ki67), apoptosis (TUNEL), and nuclear expression of ERα, PGR, PTEN, and KLF9 proteins in tumor glandular epithelial (GE) and stromal (ST) cells." (PMID 32046384, 2020). "Coupled with the ability of KLF9 to interact with other members of the Sp/KLF family, progesterone receptors, and receptor co-activators and co-repressors, our data suggest expanded possibilities for KLF9 to affect distinct physiological processes as well as the genesis of endometrial tumors." (PMID 18783612, 2008).
hyperthyroidism (4 papers, 2014 to 2024). Overactivity of the thyroid gland resulting in overproduction of thyroid hormone and increased metabolic rate. "KLF9 is demethylated in response to thyroid hormone, and the differential methylation identified in our study is likely a reflection of hyperthyroidism and hypothyroidism in the GD and HD groups, respectively." (PMID 37962983, 2024). "Previous studies on mice demonstrated that hyperthyroidism and hypothyroidism in specific regions of the brain alter the expression of specific TH-induced genes, such as Kruppel-like factor 9 (klf9) and neurogranin (RC3/nrgn)." (PMID 25255244, 2014). "In bone tissue of Bmpr1afl/fl;Osx-Cre mice, Bmpr1a expression tended to decrease in mice with active Cre-recombinase (−59.4%, P = 0.07) and Klf9 expression was upregulated by 78.4% with hyperthyroidism as compared with Cre-negative, euthyroid mice." (PMID 38719881, 2024). "As already reported the newborn Mct8KO mice showed an unexpected cerebral cortex hyperthyroidism as reflected in the expression of the thyroid hormone-regulated genes Hr, Sema7a, and Klf9, which is not due to immaturity of the brain barriers." (PMID 24819605, 2014).
liver cancer (4 papers, 2020 to 2023). An epithelial or non-epithelial malignant neoplasm that arises from the liver. "In the past few years, KLF9 has been reported to be associated with colorectal, breast, prostate, and liver cancers." (PMID 37644041, 2023). "KLF9 is implicated in suppression of liver cancers and other malignancies." (PMID 35406507, 2022). "To study the role of KLF9 in liver cancer metastasis, we first tested the functions of KLF9 in cell migration and invasion in vitro." (PMID 37400979, 2023). "Effects of KLF9 on liver cancer metastasis and EMT are still elusive, and we originally uncovered that KLF9 functionally suppresses HCC metastasis and EMT in this study, which will be a novel therapeutic target for drug development." (PMID 37400979, 2023). "Consistent with the change in the mRNA level, the protein level of KLF9 was also increased while the metastatic ability of liver cancer cells weakened." (PMID 37400979, 2023). "To examine the role of KLF9 in metastasis of liver cancer cells, we first applied an intracardiac injection‐based experimental metastasis assay in both LM and Lo cells." (PMID 37400979, 2023). "In animal models of hepato-carcinogenesis, T3 treatment impeded liver cancer development, in parallel with inductions in Klf9 gene expression." (PMID 35406507, 2022). "We next investigated if KLF9 affects tumour growth and metastasis of liver cancer in vivo." (PMID 37400979, 2023). "The interesting anticorrelation between KLF9 expression and liver cancer metastasis suggested that KLF9 may be a negative regulator in liver cancer metastasis." (PMID 37400979, 2023). "More strikingly, the expression of KLF9 was further downregulated in the patients who developed intrahepatic metastasis at diagnosis compared to patients who did not have metastatic diseases, further suggesting an antimetastasis role of KLF9 in liver cancer." (PMID 37400979, 2023). "To further validate the function of KLF9 in HCC metastasis, we applied an orthotopic metastasis assay, which can more faithfully indicate and represent the metastatic capacity of liver cancers." (PMID 37400979, 2023).
pulmonary fibrosis (4 papers, 2020 to 2025). Chronic progressive interstitial lung disorder characterized by the replacement of the lung tissue by connective tissue, leading to progressive dyspnea, respiratory failure, or right heart failure. "Furthermore, it has been shown that Klf9-deficient mice confer resistance to bleomycin-induced oxidative stress and pulmonary fibrosis." (PMID 35455944, 2022). "Klf9-mediated oxidative stress was evaluated in vivo using bleomycin-induced pulmonary fibrosis model mice, and Klf9-KO mice exhibited a decrease in 8-OHdG levels and fibrosis." (PMID 32079324, 2020). "NFE2L2 (NF-E2–related transcription factor 2, also called NRF2) stimulation increases the expression of KLF9 (Kruppel-like factor 9), resulting in increases in ROS production and subsequent cell death, however they show diverse functions in bleomycin-induced pulmonary fibrosis in mice and IPF." (PMID 35980387, 2022).
Anxiety (3 papers, 2010 to 2023). Intense feelings of nervousness, tension, or panic often arise in response to interpersonal stresses. "Murine studies find associations with Klf-9 and anxiety, and human studies link Klf-11 with chronic stress and depressive disorders." (PMID 29225348, 2017). "Consistently, in Klf-9-null mice decreased differentiation and plasticity of adult born neurons elicit anxiety which is also only detectable in a dark-light-paradigm and not in other anxiety-related tests." (PMID 20862278, 2010). "Experiments involving Klf9 knock-out (KO) mice highlighted the essential role of the gene in hippocampal (DG) dendritic spine differentiation, neuronal maturation, synaptic plasticity, anxiety-like behaviours, and learning." (PMID 36942087, 2023). "Pathway analysis of ChIP- and RNA-seq datasets predicted a role of Klf9 and Klf15 in neurobiological functions, such as neuronal development and synaptic plasticity and in behavioural processes such as learning, cognition and anxiety." (PMID 36942087, 2023).
colon tumor (3 papers, 2008 to 2023). "Heterozygous and homozygous knockouts of the Klf9 gene in the background of the ApcMin/+ mutation led to significantly more colon adenomas in both male and female mice, further supporting the colon tumor-suppressive role of KLF9." (PMID 38067370, 2023). "Moreover, miR-215 and miR-93 were reported to potentially regulate the Kruppel-like factor 9 (KLF9), that is downregulated in the epithelium in human colon cancer." (PMID 28878141, 2017). "While this association is not particularly strong and requires additional confirmation with increased sample size and evaluation at the protein level, our data mirrors a recent report that decreased KLF9 expression also is a feature of increased grade of colon tumors." (PMID 18783612, 2008).
Hypoglycemia (3 papers, 2021 to 2023). A decreased concentration of glucose in the blood. "Specifically, both global and hepatocyte-specific Klf9 KO mice (Alb-Klf9−/−) displayed hypoglycemia upon fasting because of suppressed hepatic gluconeogenesis." (PMID 36902112, 2023). "PGC-1α overexpression in Alb-Klf9−/− mice rescued fasting-induced hypoglycemia." (PMID 36902112, 2023).
hypothyroidism (3 papers, 2014 to 2024). Abnormally low levels of thyroid hormone. "At the transcriptional level, expression of Klf9 decreased by 40.83%, while expression of Glut1, Pparg, and Il-1b increased due to hypothyroidism." (PMID 36143246, 2022). "Within eWAT, low expression of Klf9 while high expression of deiodinase 2 (Dio2), an enzyme that can convert T4 to T3, indicated local hypothyroidism in treated mice." (PMID 36143246, 2022). "RNA expression analysis revealed downregulated levels of thyroid hormone target gene Klf9 transcripts by 52.01%, indicating local hypothyroidism, in muscle tissue, while myogenic marker genes MyoD1 and Myog were not affected by hypothyroidism." (PMID 36143246, 2022). "In BAT, we found reduced Klf9 (−34.82%) expression and 2.51-fold increased mRNA levels of Ucp1, the master regulator of brown adipocyte thermogenesis, although Prdm16, the transcriptional coregulator of brown adipocyte differentiation, and Ppargc1a were not regulated by hypothyroidism." (PMID 36143246, 2022).
myocardial infarction (3 papers, 2025). Gross necrosis of the myocardium, as a result of interruption of the blood supply to the area, as in coronary thrombosis. "Interestingly, the loss of Klf9 suppresses the inflammatory responses of macrophages triggered by myocardial infarction via the inhibition of NF-ĸB activation and MAPK signaling." (PMID 40643515, 2025). "KLF9 has been identified as a pro-inflammatory transcription factor in macrophages during myocardial infarction." (PMID 40860800, 2025). "In inflammatory settings such as myocardial infarction, KLF9 acts as a pro-inflammatory amplifier by directly activating NF-κB via TLR2, driving cytokine storms and tissue damage." (PMID 40860800, 2025). "Also, aberrant upregulated Klf9 has been observed after myocardial infarction (MI), resulting in inflammatory responses and cell damage." (PMID 40643515, 2025).
osteoarthritis (3 papers, 2022 to 2025). A noninflammatory degenerative joint disease occurring chiefly in older persons, characterized by degeneration of the articular cartilage, hypertrophy of bone at the margins and changes in the synovial membrane. "The silencing of EPYC and the overexpression of KLF9 are associated with the occurrence of osteoarthritis and immunocyte infiltration." (PMID 35902862, 2022). "Kruppel-like factor 9 (KLF9) is involved in the development of osteoarthritis (OA), which is a chronic joint disorder." (PMID 40533763, 2025). "EPYC and KLF9 can be viewed as feature genes for osteoarthritis." (PMID 35902862, 2022).
adenoma (2 papers, 2018 to 2023). A neoplasm arising from the epithelium. "In the classical ApcMin/+ mouse model of intestinal cancer, KLF9 immunoreactivity was low to undetectable in adenomas of the ileum, but was detected in the crypts and villus lamina propria cells of the adjacent normal-appearing mucosa." (PMID 38067370, 2023). "Male ApcMin/+/ME1-Tg mice exhibited greater small intestine crypt depth and villus length in non-adenoma regions, correspondent with increased KLF9 protein abundance in crypts and lamina propria." (PMID 30250042, 2018). "Moreover, KLF9 immunostaining in adenomas was negligible in both mouse lines." (PMID 30250042, 2018). "We speculate that the enhanced frequency of KLF9-positive cells in the small intestine crypts is growth-promoting for normal appearing and transitional villi, whereas KLF9 exerts tumor-suppressive actions in adenomas of the colon but not small intestine." (PMID 30250042, 2018).
Bladder Urothelial Carcinoma (2 papers, 2023 to 2024). "In addition, KLF9 has been reported to participate in coregulatory ceRNA interactions in bladder urothelial carcinomas." (PMID 38627780, 2024).
breast invasive carcinoma (2 papers, 2016 to 2023). "Based on publicly available RNA-seq datasets from the GTEx and TCGA breast invasive carcinoma, we found that KLF9 expression is significantly downregulated in tumor samples in comparison to normal tissue controls." (PMID 36823570, 2023).
breast tumor (2 papers, 2014 to 2023). "Notably, the pattern of KLF9 downregulation in breast tumor samples was reflected by the cell models used, confirming the validity of these lines in recapitulating molecular events in vivo and further highlighting the potential anti-tumorigenic role of KLF9 in BCa." (PMID 36823570, 2023).
cutaneous squamous cell carcinoma (2 papers, 2021 to 2022). "In conclusion, PFKFB3 was transcriptionally regulated by KLF9, and PFKFB3 silencing inhibits the proliferation, metastasis, and aerobic glycolysis of cutaneous squamous cell carcinoma cells." (PMID 34612136, 2021). "Taken together, KLF9-induced PFKFB3 downregulation inhibits the proliferation, metastasis and aerobic glycolysis of cutaneous squamous cell carcinoma cells." (PMID 34612136, 2021).
endometrial adenocarcinoma (2 papers, 2014 to 2022). "A previous study has identified KLF9 as a direct PR-interacting protein that functions as a transcriptional repressor at the node of the PR and ER genomic pathways to influence cell proliferation in the human endometrial adenocarcinoma cell line." (PMID 36552817, 2022).
esophageal squamous cell carcinoma (2 papers, 2021 to 2023). Esophageal squamous cell carcinoma (ESCC) is a type of esophageal carcinoma (EC) that can affect any part of the esophagus, but is usually located in the upper or middle third. "In esophageal squamous cell carcinoma, lower KLF9 expression was associated with cancer metastasis and tumor stage/size." (PMID 37833790, 2023). "A previous study also noted decreased KLF9 expression in esophageal squamous cell carcinoma (ESCC), and suggested the notion that KLF9 inhibited the growth and metastasis of ESCC cells." (PMID 34612136, 2021).
gestational diabetes mellitus (2 papers, 2023 to 2024). "Reduced levels of TNF-α, IL-1β, and IL-6 during KLF9 silencing suggest suppressed inflammation in gestational diabetes mellitus." (PMID 37940560, 2023).
heart failure (2 papers, 2023 to 2025). Inability of the heart to pump blood at an adequate rate to meet tissue metabolic requirements. "Correspondingly, we also found that KLF9 deficiency aggravates the deterioration of heart failure." (PMID 40198141, 2025). "Therefore, KLF9 deficiency causes the accumulation of dysfunctional mitochondria and accelerates heart failure in response to angiotensin II treatment." (PMID 40198141, 2025). "As well as Klf4, Klf6, and Klf9 showed an enriched expression in cells from patients with heart failure compared with the healthy human heart." (PMID 36082978, 2023).
medullary thyroid carcinoma (2 papers, 2023 to 2025). "Recent research has shown that the small molecule ONC201 can induce apoptosis in medullary thyroid carcinoma cells by regulating KLF9 among other targets." (PMID 40860800, 2025). "KLF9, a target gene of TF4, can induce cell apoptosis in medullary thyroid carcinoma." (PMID 37817224, 2023).
Multiple myeloma (2 papers, 2023 to 2025). "A genomic region of homozygosity (ROH) at chromosome 9q21, containing KLF9, showed a consistent association with multiple myeloma risk in genome-wide analyses." (PMID 40860800, 2025). "In multiple myeloma, KLF9 has been implicated in regulating tumor cell behavior through its interactions with long non-coding RNAs and microRNAs." (PMID 40860800, 2025). "For example, lncRNA DANCR has been shown to regulate KLF9 expression by sponging miR-135b-5p, which in turn affects the viability and invasiveness of multiple myeloma cells." (PMID 40860800, 2025). "Collectively, KLF9 plays its role in multiple myeloma as both a mediator of therapeutic response (via HDAC inhibitor-driven NOXA activation) and a potential genetic risk marker linked to the 9q21 ROH locus." (PMID 40860800, 2025). "Multiple myeloma patients responding to the proteasome inhibitor bortezomib exhibited higher basal KLF9 expression." (PMID 40860800, 2025). "Moreover, KLF9 also sensitized MDA-MB-231 cells to DOX-induced apoptosis, likely mediated through a similar KLF9-dependent upregulation of pro-apoptotic NOXA in multiple myeloma cells and yet other unidentified factors mediating response to genotoxic stress." (PMID 36823570, 2023).
nasopharyngeal carcinoma (2 papers, 2021 to 2025). A carcinoma arising from the nasopharyngeal epithelium. "In nasopharyngeal carcinoma (NPC), KLF9 exhibited a unique pro-tumorigenic role by orchestrating macrophage dysfunction within the tumor microenvironment." (PMID 40860800, 2025).
prostate tumor (2 papers, 2017 to 2023). "Whereas genes associated with factors suppressing prostate tumor growth and metastasis like Klf9, and Gpr68 were decreased in MLL- vs. AT1-LNs." (PMID 28472073, 2017). "Similar to KLF9, KLF13 mRNA and protein levels are significantly lower in prostate tumors than in adjacent non-tumor tissue." (PMID 38067370, 2023).
testicular seminoma (2 papers, 2020 to 2023). A malignant germ cell tumor arising from the testis. "KLF9 mRNA abundance was significantly reduced in testicular seminomas when compared to precancerous matched normal tissue, with the more advanced tumors displaying a further reduction in the levels of KLF9 mRNA." (PMID 38067370, 2023).